LGALS4 (galectin 4)
Diseases named in the same sentence as LGALS4 in open-access papers (continued):
Sharing a sentence is not in itself a finding about the gene and the disease.
gastric cancer (continued). "To elucidate the mechanisms involved in galectin-4-mediated regulation with respect to glycosylation, we first performed N-glycomics of membrane proteins (hydrophobic fraction) of wild-type and galectin-4 KO clones of the poorly differentiated gastric cancer cell line NUGC4." (PMID 37569679, 2023). "Galectin-3 and galectin-4 may be useful tumor markers for gastric cancers with respect to tumor progression and potentiality of lymph node metastasis especially in certain histological types of gastric cancer." (PMID 24339967, 2013). "Validation of the RIPK genes through GEPIA identified 8 genes (NRP1, MNX1, SSRP1, PRDX2, PLRG1, LGALS4, SNX5 and FXYD3) which are highly expressed in stomach cancer were significantly down-regulated in PRU treated samples." (PMID 35831348, 2022). "Specifically, 8 genes NRP1, MNX1, SSRP1, PRDX2, PLRG1, LGALS4, SNX5 and FXYD3) which are highly expressed in stomach cancer were significantly down-regulated in PRU treated samples." (PMID 35831348, 2022). "Specifically, 8 genes (NRP1, MNX1AS1, SSRP1, PRDX2, PLRG1, LGALS4, SNX5 and FXYD3) were found to be highly expressed in stomach cancer tissues compared to normal tissues." (PMID 35831348, 2022). "We investigated the glycan profiles of cell surface proteins and GSLs of the cells with different galectin-4 expression and metastatic potential and found that galectin-4 is involved in the structural changes of GSL glycans in poorly differentiated gastric cancer cells." (PMID 37569679, 2023). "In our previous study, we observed that galectin-4, but not galectin-3, was highly expressed in poorly differentiated gastric cancer cells with high metastatic potential." (PMID 37569679, 2023). "Galectin-4 further contributes to peritoneal metastasis through interactions with specific membrane proteins such as mesenchymal–epithelial transition factor (c-MET) and CD44, both of which are known to be involved in gastric cancer progression and epithelial-to-mesenchymal transition." (PMID 40710343, 2025).
Obesity (13 papers, 2017 to 2025). Accumulation of substantial excess body fat. "In addition, galectin-4 has been reported to be associated with hospitalization linked to obesity and ST-segment elevation myocardial infarction." (PMID 38811951, 2024).
diabetes (12 papers, 2018 to 2025). "In previous epidemiological studies, we have shown that increased levels of galectin-4 (Gal-4) are linked with prevalent and incident diabetes, as well as increased risk of future myocardial infarction, heart failure, cardiovascular, and all-cause mortality." (PMID 37373212, 2023). "An association between high Galectin-4 (Gal-4) and prevalence of diabetes in subjects with heart failure (HF) has previously been reported." (PMID 37985679, 2023). "Epidemiological studies have associated plasma galectin-4 (Gal-4) levels with prevalent and incident diabetes, and with an increased risk of coronary artery disease." (PMID 37373212, 2023). "Galectin-4, with an increased risk of diabetes, and Paraoxonase type 3, with a decreased risk of diabetes, remained significantly associated with incident diabetes after adjusting for plasma glucose, implying a glucose independent association with diabetes." (PMID 30670722, 2019). "Twenty-six proteins were positively associated with diabetes, including cathepsin D, retinal dehydrogenase 1, α-l-iduronidase, hydroxyacid oxidase 1 and galectin-4 (top five findings)." (PMID 31446444, 2019). "Following further adjustment of the model for BMI, smoking status, lipid measurements, hypertension, and diabetes status, the quantitative difference of galectin-4 for CHD and NCK1 for CIMT remained significant." (PMID 38811951, 2024). "This association was only significant in subjects with diabetes, implying a role for Galectin-4 in diabetes and its complications." (PMID 35780152, 2022).
colitis (8 papers, 2008 to 2025). Inflammation of the colon. "Galectin 4 (Gal-4) is associated with an increase in the pro-inflammatory interleukin 6 (IL-6) during colitis, while Galectin 9 (Gal-9) is associated with an increase in the anti-inflammatory role during EAE by favoring the apoptosis of Th1 cells." (PMID 40650248, 2025). "Galectin-4 was demonstrated to exacerbate intestinal inflammation by directly stimulating the CD4+ T cells to produce IL-6 on TCR mutational colitis model." (PMID 27017379, 2016). "Indeed, it has been shown in a TCR mutational colitis mouse model that galectin-4 can trigger IL-6 expression/secretion from activated CD4+ T cells." (PMID 36139125, 2022). "Contrarily, galectin-4 has also been described as an anti-inflammatory agent by selectively modulating T-cell responses in an experimental colitis model." (PMID 33805597, 2021). "Besides its role in the stabilization of lipid rafts, apical protein trafficking and cell adhesion, galectin-4 was shown to exacerbate intestinal inflammation by stimulating CD4+ T-cells to produce IL-6 in a murine colitis model." (PMID 33805597, 2021). "However, a later study reported that galectin-4 had the capacity to reduce mucosal inflammation and induce T-cell apoptosis in a colitis model." (PMID 26828567, 2016). "Based on the existing data, we can conclude that galectin-4 may exacerbate intestinal inflammation in TCR mutational colitis model, while ameliorate intestinal inflammation in wild-type colitis model." (PMID 27017379, 2016). "Furthermore, galectin-4 regulates the pathogenesis of inflammatory bowel diseases and colitis." (PMID 36873388, 2023). "This was dependent on distinct intestinal inflammatory conditions, and the experimental model analyzed, which could explain why Paclik and coauthors in a wild-type colitis model demonstrated that galectin-4 reduced the secretion of IL-6 as well as TNF-α, CXCL8, IL-10, by activated T cells." (PMID 36139125, 2022). "Galectin-4 activates CD4+ T cells and IL-6 secretion that contributes to the progression of colitis in mice." (PMID 36873388, 2023). "Lately, an inducible colitis-associated glycome (CAG), which contains an immature (nonsialylated) core-1 O-glycan expressed by CD4+ T cells, was identified as a ligand of galectin-4 under intestinal inflammatory conditions." (PMID 27017379, 2016). "Thus, galectin-4 may activate the PKCθ by binding to CAG and, then contributing to exacerbation of colitis." (PMID 27017379, 2016).
pancreatic adenocarcinoma (8 papers, 2007 to 2021). "Galectin-4 (Gal-4) is a member of the galectin family of glycan binding proteins that shows a significantly higher expression in cystic tumors of the human pancreas and in pancreatic adenocarcinomas compared to normal pancreas." (PMID 23824659, 2013). "These genes include many not previously associated with pancreatic adenocarcinoma, such as galectin-4 (LGALS4), mucin 13 (MUC13), secretory leukocyte protease inhibitor (SLPI), collagen 17A1 (COL17A1), and ropporin 1-like (ROPN1L)." (PMID 17389914, 2007).
prostate carcinoma (8 papers, 2011 to 2025). A carcinoma that arises from epithelial cells of the prostate gland. "Our study suggested a significant correlation between the upregulation of MTHFD1 and LGALS4 and an increased risk of prostate cancer." (PMID 39857769, 2025). "Some studies reported that the high expressions of T antigen is highly associated with the metastatic and poor survival in prostate cancer and the interaction between galectin-4 and T antigen may contribute to this process." (PMID 31355147, 2019). "In prostate cancer cells, C1GALT1 regulates EGFR O-glycosylation to enhance galectin-4-mediated phosphorylation of EGFR." (PMID 29930379, 2018). "In summary, the targeting of LGALS4 or MTHFD, in combination with ADT, chemotherapy, and immunotherapy, could offer a novel approach to treating prostate cancer, particularly in cases where resistance to current therapies limits clinical efficacy." (PMID 39857769, 2025). "Therefore, targeting LGALS4 could improve the efficacy of ICIs and ATD in prostate cancer, especially in metastatic or castration-resistant cases." (PMID 39857769, 2025). "It was reported that C1GALT1 knockdown decreases galectin-4-mediated but not ligand-mediated EGFR phosphorylation and downregulates EGFR protein levels in prostate cancer cells." (PMID 29930379, 2018).
colon adenocarcinoma (7 papers, 2009 to 2023). "As to COAD(Colon adenocarcinoma), LGALS4 is associated with the colon." (PMID 34149811, 2021). "Diseases associated with LGALS4 include colon adenocarcinoma and measles." (PMID 26964035, 2016). "LGALS4 is associated with multiple cancer types and is a possible prognostic and diagnostic marker of colon adenocarcinoma (COAD)." (PMID 36941538, 2023). "Furthermore, galectin-4 protein overexpression has been demonstrated in colon adenocarcinoma, and ductal and lobular carcinomas of the breast by using immunohistochemical analysis." (PMID 24339976, 2013).
lung carcinoma (7 papers, 2014 to 2025). "Contrarily, other studies have shown that in the lung cancer cohort of smokers, the LGALS4 gene is hypermethylated and downregulated, suggesting its function is suppressed." (PMID 40134029, 2025). "All these findings show that galectin-1, galectin-3, and galectin-8 are the most abundantly expressed galectins while the expression of galectin-4, galectin-7, and galectin-9 is relatively low, both in tumor tissues and in different lung cancer cell lines." (PMID 25259711, 2014). "More recently, elevated levels of galectin-1 expression were found to promote lung cancer progression and chemoresistance while increased galectin-4 expression was shown to predict lymph node metastasis in adenocarcinoma of the lung." (PMID 25259711, 2014). "In particular, human galectin-4, normally expressed in the healthy gastrointestinal tract, displays differential expression in cancerous tissues and is considered a potential drug target for liver and lung cancer." (PMID 27642006, 2016).
heart failure (6 papers, 2023 to 2025). Inability of the heart to pump blood at an adequate rate to meet tissue metabolic requirements. "Another study compared heart failure patients to controls both recruited in the outpatient clinic at Karolinska University Hospital, finding galectin-4 to be significantly associated with heart failure (HR = 2.6; FDR adjusted p-value 0.005)." (PMID 38811951, 2024). "A Swedish population-based study found galectin-4 to be significantly associated with incident coronary events (hazard ratio (HR) = 1.34, 95% confidence interval (CI) = 1.14–1.57) and incident heart failure (HR = 1.26, 95% CI 1.03–1.54)." (PMID 38811951, 2024). "In plasma proteome analysis of patients with heart failure, diabetic patients had higher circulating GDF-15 and galectin-4 levels, and over-representation of pathways related to inflammation, cardiac remodeling, and fibrosis." (PMID 36765354, 2023).
inflammatory bowel disease (6 papers, 2008 to 2025). A spectrum of small and large bowel inflammatory diseases of unknown etiology. "These molecules have potential as lead compounds towards discovery of galectin-4-targeting compounds addressing inflammatory conditions, such as inflammatory bowel disease and ulcerative colitis." (PMID 40735388, 2025). "Overall, LGALS4 plays a critical role in gastrointestinal physiology and may have implications for diseases such as inflammatory bowel disease and cancer." (PMID 38612533, 2024). "Conclusively, after defining its biological role, we propose Galectin-4 is a novel anti-inflammatory agent that could be therapeutically effective in diseases with a disturbed T cell expansion and apoptosis such as inflammatory bowel disease." (PMID 18612433, 2008).
ovarian carcinoma (6 papers, 2006 to 2023). A malignant neoplasm originating from the surface ovarian epithelium. "In total patients with ovarian cancer, LGALS4, LGALS8, LGALS10 and LGALS13 mRNA levels were related to a better OS, and LGALS1 to a worse OS." (PMID 33854625, 2021). "Galectin-3 can be a tool to distinguish the proactive and active forms of MMP-2 and -9 and galectin-4 as a marker of MOC in ovarian cancer." (PMID 23658855, 2010). "We therefore examined the expression of LGALS4 in ovarian carcinoma using immunohistochemistry." (PMID 16508639, 2006). "LGALS1, LGALS3, LGALS4, LGALS8 and LGALS9 were found to be overexpressed in ovarian cancer patients." (PMID 37238197, 2023). "LGALS1, LGALS3, LGALS4, LGALS8, and LGALS9 were found to be mostly overexpressed in ovarian carcinoma patients with the following percentage: 78.6%, 92.9%, 66.1%, 87.5%, and 85.7% respectively." (PMID 36050693, 2022). "LGALS4 predicted a better OS in patients with endometrioid, stages I+II or grade III ovarian cancer." (PMID 33854625, 2021). "The mRNA expression of LGALS4, LGALS10 and LGALS13 were all significantly downregulated in the human ovarian cancer cell lines in comparison with those in normal ovarian cell line (P < 0.05)." (PMID 33854625, 2021). "In the present study, the mRNA expression of five galectins (LGALS1, LGALS3, LGALS4, LGALS8, and LGALS9) is explored in the tumor samples of 56 ovarian carcinoma patients, and the expression fold change was calculated in comparison to 26 adult females with normal ovaries." (PMID 36050693, 2022). "Regarding with different clinical stages of ovarian cancer, it was observed that elevated LGALS8 and LGALS10 mRNA expression predicted a better OS in patients with stages I+II as well as with stages III+IV, and LGALS4 predicted a better OS in patients with stages I+II." (PMID 33854625, 2021). "Moreover, we also showed that LGALS4 is consistently highly expressed in MOC but is absent in the other histological subtypes of ovarian cancer and normal ovaries using immunohistochemistry, thus confirming the transcript profiling results." (PMID 16508639, 2006). "The protein level of LGALS1, LGALS4, LGALS8, LGALS10 and LGALS13 in ovarian cancer cell lines were all decreased compared with those in the normal ovarian cell (all P<0.05)." (PMID 33854625, 2021).
hepatocellular carcinoma (5 papers, 2012 to 2024). A malignant tumor that arises from hepatocytes. "Similarly, in hepatocellular cancer, the low level expression of galectin-4 contributes to increased metastasis and progression of the cancer." (PMID 27017379, 2016).
lymph node metastasis (5 papers, 2013 to 2025). "Galectin-4 was strongly expressed in LUAD patients with lymph node metastasis and was associated with aggressive cancer traits such as lymphatic and venous invasion, although it did not correlate with overall or recurrence-free survival." (PMID 40718829, 2025). "The promoter hypermethylation of LGALS4 (>2.51, log10 scale) revealed a positive correlation with high levels of both histological grade and tumor T category and with lymph node metastasis (all P≤0.001)." (PMID 28423602, 2017). "By the multivariate analysis, Galectin-4 expression was revealed as one of the independent predictor for lymph node metastasis, together with solid predominant and micropapillary histologic pattern." (PMID 24339976, 2013). "Furthermore, galectin-4 expression was revealed to be an independent predictor for lymph node metastasis and an adverse survival factor in patients with lung adenocarcinoma of acinar predominant type." (PMID 24339976, 2013). "By the multivariate analysis, galectin-4 expression was revealed as an independent predictor with intermediate power for lymph node metastasis, although the odds ratio was lower than those of histological features (solid predominant and micropapillary pattern)." (PMID 24339976, 2013).
atherosclerosis (3 papers, 2023 to 2024). A disease characterized by the build-up of fatty material and calcium deposition in the arterial wall resulting in partial or complete occlusion of the arterial lumen. "Galectin-4 may be involved in atherosclerosis by enhancing lipid raft stabilization, which may subsequently affect redox signaling pathways." (PMID 38811951, 2024). "Galectin-4 may be involved in atherosclerosis by enhancing lipid raft stabilization, which subsequently affects redox signaling pathways." (PMID 38811951, 2024).
lung adenocarcinoma (3 papers, 2013 to 2024). A carcinoma that arises from the lung and is characterized by the presence of malignant glandular epithelial cells. "We observed that 148 lung adenocarcinomas (20.9%) expressed galectin-4, which was significantly associated with variables of disease progression such as tumor size (p<0.0001), pleural invasion (p = 0.0071), venous invasion (p = 0.0178), nodal status (p = 0.0007), and TNM stage (p<0.0001)." (PMID 24339976, 2013). "Using the κ2 test, galectin-4 expression was found to be associated with the nodal status (p<0.0001) in adenocarcinomas of acinar predominant subtype, which is the most common subtype of invasive lung adenocarcinomas." (PMID 24339976, 2013). "Galectin-4 expression was associated with the presence of venous invasion, but not with the presence of lymphatic invasion, speculation follows that Galectin-4 may develop metastasis of lung adenocarcinoma cells via venous invasion." (PMID 24339976, 2013). "We immunohistochemically evaluated the clinicopathological significance of galectin-4 in lung adenocarcinoma." (PMID 24339976, 2013). "It is unclear how galectin-4 is involved in the acquisition of metastatic potential in lung adenocarcinoma cells." (PMID 24339976, 2013). "From 707 lung adenocarcinoma samples, 148 adenocarcinomas from 147 patients showed galectin-4 expression (20.9%)." (PMID 24339976, 2013). "The predictive value of galectin-4 was confirmed by immunohistochemical analysis for a validation set consisting of 707 surgically resected specimens of lung adenocarcinomas (stages I to IV)." (PMID 24339976, 2013). "We found that galectin-4 was one of the independent predictor for LN metastasis in lung adenocarcinoma." (PMID 24339976, 2013). "The present study showed that galectin-4 is localized to the cytoplasm, nucleus, and focal membranes in lung adenocarcinomas." (PMID 24339976, 2013). "In conclusion, this study describes the possible metastasis-promoting role of galectin-4 in lung adenocarcinoma." (PMID 24339976, 2013). "Our findings demonstrate that galectin-4 can be a useful biomarker for predicting LN metastasis as well as a potential prognostic factor for patients with lung adenocarcinoma of acinar predominant type." (PMID 24339976, 2013). "Especially, galectin-4 is a protein belonging to the galectin family which are known to play a role in cancer cell activities and little is known about galectin-4 expression in lung adenocarcinoma." (PMID 24339976, 2013). "Galectin-4 plays an important role in metastatic process of lung adenocarcinoma." (PMID 24339976, 2013). "Additionally, specific lung adenocarcinoma subtypes, including 19 invasive mucinous adenocarcinomas (67.9%), and 2 colloid carcinomas (100%), expressed galectin-4." (PMID 24339976, 2013). "Immunohistochemical testing for galectin-4 expression may be useful together with the detection of specific histology to predict the metastatic potential of lung adenocarcinoma." (PMID 24339976, 2013). "Furthermore, logistic regression analysis showed that galectin-4 expression could independently predict LN metastasis in patients with lung adenocarcinomas (p = 0.0021)." (PMID 24339976, 2013). "Our study included 21 patients with 2 primary lung adenocarcinoma lesions in the same lobe; both lesions from 1 patient showed galectin-4 expression, whereas none of the adenocarcinomas in the remaining 20 patients showed galectin-4 expression." (PMID 24339976, 2013). "Using 2D SDS-PAGE and mass spectrometry, galectin-4 was observed to be differentially expressed in lung adenocarcinomas with and without LN metastasis." (PMID 24339976, 2013).